STAT1 (signal transducer and activator of transcription 1)
Diseases named in the same sentence as STAT1 in open-access papers (continued):
Sharing a sentence is not in itself a finding about the gene and the disease.
lung cancer (continued). "Activation of the interferon/STAT1 pathway has been reported to correlate with resistance to radiotherapy, doxorubicin chemotherapy, and cetuximab target therapy in lung cancer." (PMID 23451142, 2013). "Additionally, ROP16 can polyubiquitinate STING, inhibiting the cGAS-STING signaling pathway, reducing inflammatory cytokine secretion, and inhibiting STAT1 and NF-κB pathways, ultimately preventing brain metastasis of breast and lung cancer." (PMID 40684184, 2025). "Due to SP140’s ability to enhance STAT1/IRF1 signaling and increase PD-L1 expression in tumor-associated macrophages, it has emerged as a crucial biomarker of immune evasion and predictor of immunotherapy resistance in cancers such as HNSCC and lung cancer." (PMID 41188771, 2025). "Recently, we discovered a dependency of cancer persistence on type I PRMTs in lung cancer cells with high STAT1 signaling levels, which can arise from a number of factors, including intrinsic cancer cell signals, microenvironmental cytokines, and/or treatment-induced adaptation." (PMID 39699269, 2025). "Collectively, the findings suggested that QFM may increase the influences of PD-1 inhibitors at least partially by blocking the STAT1/IDO1-mediated tryptophan-kynurenine pathway in lung cancer." (PMID 38882349, 2024). "Moreover, we previously found that STAT1 is one of the core targets of QFM against lung cancer according to network pharmacology and bioinformatics analyses." (PMID 38882349, 2024). "STAT1 is a known transcription factor with roles in both asthma and lung cancer pathogenesis." (PMID 35406434, 2022). "Western blot analysis indeed revealed that Daidzein and Gefitinib combination treatment synergistically inhibited multiple EGFR phosphorylation sites (P-EGFR Y1068, T845 and T1092) in both A549 and H1975 lung cancer cells, which led to deactivation of STAT1 and STAT3." (PMID 35813479, 2022). "Moreover, DNAJB4 overexpression can inhibit the proliferation, tumorigenesis, cell mortality, and invasion of lung cancer cells by reducing cyclin D1 expression, increasing STAT1 and p21WAF1 expression, and then activating the STAT1 pathway." (PMID 36499297, 2022). "In addition, we also found that ADRB2 and STAT1 were significantly correlated with the prognosis of patients with lung cancer." (PMID 35127768, 2021). "Furthermore, suppression of Stat1 expression can sensitize lung cancer cells to cisplatin-induced cell death." (PMID 34685622, 2021). "The results indicated that KHSRP could interact with HNRNPC and HNRNPC may promote the metastasis of lung cancer through IFN-α-JAK-p-STAT1 signaling pathway." (PMID 31775888, 2019). "The regulation of PDL1 expression in lung cancer may depend on factors other than STAT1 and STAT2 such as NF-κB." (PMID 30305853, 2018). "Overexpression of STAT1 was observed in lung cancer progression." (PMID 27863408, 2016). "It will be interesting to look at the acetylation level of STAT1-CC in lung cancer cells." (PMID 26351076, 2015). "Results from this study suggest that combined treatment of IFNs and STAT1-CC might be a feasible approach for the clinical management of lung cancer in the future." (PMID 26351076, 2015). "Under basal culture conditions, both STAT1 and STAT1-CC have similar effects on inhibition of lung cancer cell growth, but since in the previous studies, STAT1-CC demonstrated hyper-responsive to IFN stimulation, we stimulated the cells with various concentrations of IFNs." (PMID 26351076, 2015). "It is still unclear whether using the gain-of-function of STAT1-CC could significantly improve the anti-tumor response of IFNs in lung cancer." (PMID 26351076, 2015). "Since fibronectin, β-catenin, S100A4, proliferating cell nuclear antigen (PCNA) and c-fos have been reported to be involved in the control of cell growth or metastasis in cancers, we also evaluated the effect of STAT1-CC on the expression of these proteins in lung cancer cells." (PMID 26351076, 2015).
lung cancer (continued). "Additionally, EGCG decreased STAT1 expression in A549 cells, a key oncogene in lung cancer." (PMID 40916076, 2025). "Therefore, we hypothesized that QFM may inhibit IDO1 for improving tryptophan metabolism by down-regulating STAT1 phosphorylation to decrease PD-1 expression in CD8+ T cells in lung cancer." (PMID 38882349, 2024). "Similarly, BCL3, CD44, PPARD, and STAT1 were upregulated in both the mixed group and lung cancer samples; thus, they may also be involved in the transition." (PMID 35406434, 2022). "Based on our finding that LINC00152 was mainly located in the cytoplasmic of lung cancer cells, the regulation process targeted to p38α, STAT1, CREB1 and c-MYC growth related proteins may be at the post-transcriptional level such as protein degradation mechanism." (PMID 28592840, 2017). "Together, these data suggest that combined treatment of IFNs and STAT1-CC may represent a useful therapeutic strategy for the clinical management of human lung cancer, though this approach must be evaluated for the safety and efficacy by clinical trials before any clinical applications." (PMID 26351076, 2015). "The results demonstrate that STAT1-CC has strong anti-tumor effects in lung cancer cells in response to IFNs and indicate that combined treatment of IFNs and STAT1-CC could be of potential value for further research in vivo and in an eventual therapeutic approach for treatment of human lung cancer." (PMID 26351076, 2015). "Myricetin was found to directly bind to Jak1 and has been reported to prevent the phosphorylation of STAT1 and inhibit both the expression and nuclear translocation of IRF1 to suppress IFN-γ-induced IDO1 expression in human lung cancer cells." (PMID 40002369, 2025). "In the immune microenvironment of lung cancer, IFN-γ mediates the phosphorylation of STAT1 and promotes the expression of IDO1 in LC cells." (PMID 38882349, 2024). "IFN-γ is primarily released by antigen-recognized and activated T cells, which triggers B7-H1 gene expression in lung cancer cells, cholangiocarcinoma cells, head and neck cancers, as well as HCC through the JAK/STAT1 pathway." (PMID 39070142, 2024). "The results indicated that IFNα/γ-downstream IRF1 and STAT1 both potentially mediated PD-L1 and CXCL10 expression in lung cancer." (PMID 38953994, 2024). "IFN-γ is mainly released by T cells that are recognized and activated by antigens, which can induce the expression of B7-H1 gene in lung cancer cells, bile duct cancer cells, head and neck cancers, and HCC through JAK/STAT1 pathway." (PMID 35069936, 2022). "In comparison to PC9 cells, the EGFR mutant non–small cell lung cancer (NSCLC) cells HCC4006, HCC827, and H1975 have higher levels of baseline STAT1 expression." (PMID 35089788, 2022). "The fold changes in gene expression in lung cancer relative to asthmatic cell lines were in line with the in silico prediction for the genes BCL3, CD44, PPARD, POSTN, FOSB, and STAT1." (PMID 35406434, 2022). "STAT1 has been confirmed to be under-expressed in tissue specimens of HCC, ovarian, and lung cancer and other solid tumors." (PMID 35692770, 2022). "Analysis of the enriched genes derived from the pathway analysis identified seven genes expressed in both the asthma and lung cancer sets: BCL3, POSTN, PPARD, STAT1, MYC, CD44, and FOSB." (PMID 35406434, 2022). "Analysis of the enriched genes derived from the pathway analysis identified seven genes present in both asthma and lung cancer: BCL3, POSTN, PPARD, STAT1, MYC, CD44, and FOSB." (PMID 35406434, 2022). "On analyzing data from The Cancer Genome Atlas (TCGA), we found expression levels of IRF9, STAT1, and STAT2 in patients with lung cancer, and IRF9 expression levels were positively correlated with those of STAT1 and STAT2." (PMID 33430083, 2021). "We found that IFNγ simultaneously increased phosphorylation on STAT1 and STAT3 in EGFR-positive lung cancer, resulting in overexpression of PD-L1 (p < 0.05)." (PMID 34685495, 2021).
lung cancer (continued). "Since we found that irradiation specifically suppressed STAT1 and STAT3 phosphorylation in IFNγ-treated A549 cells in this study, we speculated that STAT3 caused radioresistance was mediated by overexpression and activation of mutated EGFR in lung cancer after survived in RT treatment." (PMID 34685495, 2021). "The results suggest that A‐CpG ODNs suppress the IFN‐γ‐induced expression of PD‐L1 and β2‐MG in human lung cancer by blocking the IFN‐γ receptor and suppressing the phosphorylation of JAK/STAT1, which is regulated by the IFN‐γ signaling pathway." (PMID 32067413, 2020). "Several studies also suggested that IFNγ/STAT1 signal pathway plays a key role in inhibition of EMT in several cancers, including lung cancers, gallbladder cancer, hepatocellular carcinoma." (PMID 31113461, 2019). "Next, to investigate any correlation between CFH expression and the expression of STATs in human normal lung tissues and lung cancer tissues, the transcription level of CFH was compared with STAT1, STAT3, and STAT4." (PMID 30987235, 2019). "The protein levels of PDL1, IRF1, IRF7, STAT1, STAT2, IFNAR1, eIF2α, and ATF4 in the normal and tumor tissues of 27 subjects with lung cancer were determined by Western blot." (PMID 30305853, 2018). "Different signaling pathways such as AKT/mTOR pathway, STAT1, and STAT3 pathway, ERK pathway played a critical role in the progression of lung cancer." (PMID 29788985, 2018). "In the present study in lung cancer, LINC00152 knockdown leads to reduced several cell growth-related proteins such as STAT3, p38α, CREB1, STAT1, c-MYC and CCNE1." (PMID 28592840, 2017). "We found that expression of STAT1 or STAT1-CC enhanced the effect of IFN-γ and, IFN-β on inhibition of human lung cancer cell proliferation, migration and invasiveness." (PMID 26351076, 2015). "STAT1 or STAT1-CC inhibited SPC-A-1 and H1299 lung cancer cell growth under basal culture conditions." (PMID 26351076, 2015). "The ambivalent role of STAT1 and STAT3 in lung cancer prompted us to analyze if the TYK2-dependent activation of the reporter is mediated by STAT1 or STAT3." (PMID 24833526, 2014). "Therefore, IRF1 and STAT1 were knockdown in lung cancer A549 cells, which decreased 20 ng/mL of IFNα/γ-mediated gene expression, including IRF1, STAT1, PD-L1, CXCL10, and ISG15." (PMID 38953994, 2024). "However, the results from this study warrant further investigation into the molecular mechanisms of the four genes (PPARD, STAT1, BCL3, and POSTN) in both asthma and lung cancer cell lines, independently and in combination." (PMID 35406434, 2022). "In addition, several lncRNAs were reported to be induced by STAT1, such as lncRNA KTN1-AS1 in lung cancer and lncRNA LINC00467 in lung adenocarcinoma." (PMID 34224325, 2021). "Furthermore, OSM has been shown to regulate STAT1/3 and STAT5/6 in mouse fibroblasts and is also capable of suppressing cell motility via STAT1 activation in lung cancer." (PMID 31555281, 2019). "STAT1 and STAT3 were also tested because STAT1 was reported to be a transcription factor for CFH in response to the stimulation of IFN-γ, and STAT3 is an oncogene that is also reported to be increased in lung cancers." (PMID 30987235, 2019).
lung cancer (continued). "Furthermore, the expression of STAT1 enhanced the effect of IFN-gamma and IFN-beta on the inhibition of human lung cancer cell proliferation, migration, and invasiveness." (PMID 31083348, 2019). "Because STAT1 belongs to a genetic signature predicting lung cancer patient survival, effects of SIAH2 on STAT1 and the immunological control of tumorigenesis are possible, i.e. SIAH2 may act as tumor promoter via blocking STAT1." (PMID 24833526, 2014). "Thus, the importance of JAK signal transduction in the ability of IL-27 to activate the STAT1 and STAT3 pathways in human lung cancer was studied." (PMID 24274066, 2013). "Moreover, silibinin’s pre-treatment reduces the phosphorylation of signal transducer and activator of transcription 1 (STAT1) and signal transducer and activator of transcription 3 (STAT3) induced by cytokines responsible for the proliferation of A549 human lung cancer cells in vitro." (PMID 37915411, 2023). "HNRNPC overexpression was observed in a variety of human cancers, including lung cancer HNRNPC, as a protein-coding gene, could also interact with KHSRP to activate the IFN-α-JAK-p-STAT1 signaling pathway and promoted NSCLC cell proliferation, migration, and invasion." (PMID 34179079, 2021). "The effects of IFN signaling pathway on the PD1/PDL1 axis may not depend on STAT1 or STAT2 in lung cancer." (PMID 30305853, 2018). "Interestingly, the inhibition of STAT1 activation led to increased STAT3 activation in IL-27 treated lung cancer cells whereas inhibition of STAT3 activation alone did not significantly impact STAT1 expression." (PMID 24274066, 2013). "A strong polyI:C-induction of phosphorylated-STAT1 (p-STAT1, Ser727), STAT1, IRF5 and IRF7 protein levels was consistent with the resistance of normal Beas2B cells and the two cancer cells, HTB182 and CRL5928, to VSV infection and vice versa for the viral-sensitive lung cancer cell line." (PMID 22194884, 2011). "The PDL1 expression in lung cancer may be independent of STAT1 and STAT2." (PMID 30305853, 2018). "Overall, our findings support that STAT1, but not STAT3, plays a primary role in inhibition of pro-angiogenic factor production in human lung cancer by IL-27 treatment." (PMID 24274066, 2013). "Furthermore, only the expression of PPAR-γ and Arg1 but not other key transcription factors such as STAT1, STAT3 and C/EBPβ was dramatically reduced in Ffar2−/− MDSCs and urethane-induced lung cancer tissues." (PMID 38402237, 2024). "However, phosphorylation of STAT1 and its nuclear translocation was not always observed, for example, in IFN-β-activated lung carcinoma epithelial cells." (PMID 35409339, 2022).
glioma (84 papers, 2012 to 2025). A benign or malignant brain and spinal cord tumor that arises from glial cells (astrocytes, oligodendrocytes, ependymal cells). "Their orthotopic syngeneic glioma model demonstrated that IDH1 R132H mutation suppressed the STAT1 protein expression via 2-HG, thus decreasing the type 1-associated chemokines such as CXCL10 and affecting CD8+ T cell aggregation." (PMID 35769466, 2022). "We found that GSCs and GBM tumors exhibited differential cell-intrinsic type I and type II IFN signaling, and the high IFN/STAT1 signaling was associated with mesenchymal phenotype and poor survival in glioma patients." (PMID 34771447, 2021). "TOX expression was negatively associated with inflammatory activity signatures including HCK, LCK, MHC-I, MHC-II, STAT1, and interferon metagenes, but positively associated with the IgG metagene in pan-glioma analysis, LGG alone, and GBM alone." (PMID 32762688, 2020). "STAT2, -4, and -6 are implicated in the regulation of immune system whereas STAT1, -3, and -5 have been associated with immunological functions along with neoplastic cell transformation and growth in several tumor types, including gliomas." (PMID 31698775, 2019). "Therefore, CXCL10 production is hampered in IDH1-mutated glioma cells in a STAT1-dependent manner, seemingly correlating with reduced tumor infiltration." (PMID 35385679, 2022). "Moreover, Chinese Glioma Genome Atlas (CGGA) data showed that high STAT1 expression in GBM mesenchymal tumors was associated with poor overall survival." (PMID 34771447, 2021). "Finally, we evaluated the association of STAT1 expression with survival outcomes of glioma/GBM patients." (PMID 34771447, 2021). "The lncRNA PLAC2 induces cell cycle arrest in glioma by binding to Ribosomal Protein RP L36 in a mechanism involving STAT1." (PMID 39484215, 2024). "In both the TCGA and CGGA datasets, TREM1 expression was found to be positively correlated with HCK, interferon, LCK, MHC-I, MHC-II, and STAT1 metagenes but negatively correlated with IgG metagenes in glioma." (PMID 38370418, 2024). "The overexpression of STAT1 significantly inhibits the development of glioma cells and stimulates apoptosis in these cells." (PMID 37026000, 2023). "It has been reported that miR-525-5p negatively regulates glioma cell proliferation and epithelial mesenchymal transition, and this is mediated by targeting STAT1." (PMID 37953776, 2023). "Despite the well-established knowledge of solanine's inhibitory effects on multiple signaling pathways such as NF-κB, ERK1/2, AKT and STAT1, its precise effect on gliomas through STAT1 remains uncertain." (PMID 37865727, 2023). "Studies have also demonstrated that the expression of STAT1 is lower in gliomas than in normal brain tissues." (PMID 37026000, 2023). "Mechanistically, the epigenetic regulator MBD3, which is preferentially expressed in glioma CSCs, recruits the NuRD repressive complex to the STAT1 promoter and inhibits its expression by histone deacetylation." (PMID 35455671, 2022). "Glioma CSCs is able to evade interferon response via the downregulation of STAT1, a critical transcription factor for the induction of ISGs." (PMID 35455671, 2022). "Overexpression of STAT1 significantly inhibited the glioma cell growth and increased apoptotic cell death." (PMID 34784299, 2021).